GLYATL3 (glycine-N-acyltransferase like 3)
Description:
Catalyzes the conjugation of long-chain fatty acyl-CoA thioester and glycine to produce long-chain N-(fatty acyl)glycine, an intermediate in the primary fatty acid amide biosynthetic pathway.
Synonyms: C6orf140; bA28H17.2
Tractability: No criterion of Open Targets' tractability assessment is met for any kind of drug.
Gene: Protein-coding gene on chromosome 6 (49,499,923 to 49,528,078, forward strand). Ensembl gene ENSG00000203972.
Pathways (Reactome):
Metabolism: Conjugation of benzoate with glycine; Conjugation of carboxylic acids; Conjugation of salicylate with glycine
Drug ADME: Aspirin ADME
Gene Ontology:
Molecular function: glycine N-acyltransferase activity
Cellular component: mitochondrion
Genetic constraint (gnomAD): Loss-of-function variants: 11 observed, 9.77 expected, observed/expected ratio (o/e) 1.13, 90% interval 0.7 to 1.77. That is too few expected variants to judge how well the gene tolerates losing a copy. Missense variants: 218 observed, 221.39 expected, observed/expected ratio (o/e) 0.98, 90% interval 0.88 to 1.1. Synonymous variants: 94 observed, 93.58 expected, observed/expected ratio (o/e) 1, 90% interval 0.85 to 1.19.
Homologues: Orthologues: chimpanzee GLYATL3 (99% identical), macaque GLYATL3 (95% identical), dog GLYATL3 (89% identical), rabbit GLYATL3 (89% identical), guinea pig GLYATL3 (87% identical), rat Glyatl3 (87% identical), mouse Glyatl3 (86% identical), pig GLYATL3 (82% identical), tropical clawed frog glyatl2 (28% identical), zebrafish si:ch73-106k19.2 (28% identical), zebrafish si:dkey-76k16.6 (26% identical), zebrafish si:dkey-76k16.5 (22% identical), and 3 more. Paralogues in human: GLYATL2 (34% identical), GLYAT (34% identical), GLYATL1B (33% identical), GLYATL1 (33% identical).
Diseases named in the same sentence as GLYATL3 in open-access papers:
GLYATL3 is named in the same sentence as 1 disease in open-access papers, as found by Europe PMC text mining. Sharing a sentence is not in itself a finding about the gene and the disease.
GLYATL3 shares sentences with these, for which no sentence is quoted: cancer (1 paper).